PHAX (phosphorylated adaptor for RNA export)
Description:
A phosphoprotein adapter involved in the XPO1-mediated U snRNA export from the nucleus. Bridge components required for U snRNA export, the cap binding complex (CBC)-bound snRNA on the one hand and the GTPase Ran in its active GTP-bound form together with the export receptor XPO1 on the other. Its phosphorylation in the nucleus is required for U snRNA export complex assembly and export, while its dephosphorylation in the cytoplasm causes export complex disassembly. It is recycled back to the nucleus via the importin alpha/beta heterodimeric import receptor. The directionality of nuclear export is thought to be conferred by an asymmetric distribution of the GTP- and GDP-bound forms of Ran between the cytoplasm and nucleus. Its compartmentalized phosphorylation cycle may also contribute to the directionality of export. Binds strongly to m7G-capped U1 and U5 small nuclear RNAs (snRNAs) in a sequence-unspecific manner and phosphorylation-independent manner (By similarity). Also plays a role in the biogenesis of U3 small nucleolar RNA (snoRNA). Involved in the U3 snoRNA transport from nucleoplasm to Cajal bodies. Binds strongly to m7G-capped U3, U8 and U13 precursor snoRNAs and weakly to trimethylated (TMG)-capped U3, U8 and U13 snoRNAs. Also binds to telomerase RNA.
Synonyms: RNUXA; FLJ13193
Tractability: Small molecule: a structure with a bound ligand is known. PROTAC: ubiquitination databases record sites on it; its protein half-life has been measured.
Gene: Protein-coding gene on chromosome 5 (126,600,925 to 126,627,252, forward strand). Ensembl gene ENSG00000164902.
Subcellular location: Nucleus, nucleoplasm; Nucleus, Cajal body; Cytoplasm
Subcellular location (Human Protein Atlas): Nucleoplasm
Pathways (Reactome):
Gene expression (Transcription): RNA polymerase II transcribes snRNA genes
Metabolism of RNA: snRNP Assembly
Gene Ontology:
Molecular function: mRNA cap binding complex binding; protein binding; toxic substance binding
Biological process: RNA stabilization; snRNA export from nucleus
Cellular component: cytoplasm; nucleoplasm; ribonucleoprotein complex; cytosol; nucleus; Cajal body; neuronal cell body
Genetic constraint (gnomAD): Loss-of-function variants: 27 observed, 33.54 expected, observed/expected ratio (o/e) 0.8, 90% interval 0.59 to 1.11. The upper end of that interval is the gene's LOEUF score, 1.11, which puts it in group 4 of 6, group 1 being the genes least tolerant of losing a copy. Missense variants: 408 observed, 450.77 expected, observed/expected ratio (o/e) 0.91, 90% interval 0.83 to 0.98. Synonymous variants: 160 observed, 158.19 expected, observed/expected ratio (o/e) 1.01, 90% interval 0.89 to 1.15.
Homologues: Orthologues: chimpanzee PHAX (100% identical), macaque PHAX (98% identical), pig PHAX (91% identical), guinea pig PHAX (91% identical), rabbit PHAX (88% identical), mouse Phax (86% identical), rat Phax (86% identical), dog PHAX (85% identical), tropical clawed frog phax (60% identical), zebrafish phax (51% identical), Drosophila melanogaster Phax (29% identical), Caenorhabditis elegans Y71H2B.2 (21% identical).
Diseases named in the same sentence as PHAX in open-access papers:
PHAX is named in the same sentence as 10 diseases in open-access papers, as found by Europe PMC text mining. Sharing a sentence is not in itself a finding about the gene and the disease. The quoted sentences say what the papers report.
breast carcinoma (1 paper, 2022). "When missense variants were assessed, three further associations were observed for overall breast cancer (TMEM161A, SIPA1L1, ERCC2), and a further seven were observed for subtypes (RNF175, NCKAP1L, PHAX, SMARCA2, EML5, NTRK3, MED23)." (PMID 35884425, 2022). "Analysis of rare missense variants identified evidence of associations of TMEM161A, SIPA1L1, and ERCC2 with overall breast cancer, RNF175 and NCKAP1L with ER-positive disease, and SLC22A10, PHAX, SMARCA2, EML5, NTRK3, and MED23 with ER-negative disease." (PMID 35884425, 2022). "The best putative candidates in this group were TMEM161A, ERCC2, and SIPA1L1 for overall breast cancer, RNF175 and NCKAP1L for ER-positive disease, and PHAX, SMARCA2, NTRK3, EML5, and MED23 for ER-negative disease." (PMID 35884425, 2022).
kidney tumours (1 paper, 2020). "The exact molecular mechanism by which PHAX mediates the effect of sunitinib in controlling growth of kidney tumours is unclear, but PHAX’s physical co-localisation with the tumour vasculature suggests a hypothetical link to the drugs known anti-angiogenic properties." (PMID 32272660, 2020).
cancer (1 paper, 2020). A tumor composed of atypical neoplastic, often pleomorphic cells that invade other tissues. "PHAX knockdown in a ccRCC organ culture model impacted the ability of sunitinib to cause cancer cell death (p < 0.0001 untreated vs. treated), suggesting a role for PHAX in mediating the efficacy of sunitinib." (PMID 32272660, 2020). "In normal kidney tissue, PHAX protein abundance was low but increased with tumour grade (G1 vs. G3/4; p < 0.01), consistent with a possible role in cancer progression." (PMID 32272660, 2020).
tumour (1 paper, 2020). "ccRCC organ cultures that were UT and treated with low dose sunitinib (25 and 50 μM) showed rare to mildly infrequent expression of PHAX in CK-positive tumour cells." (PMID 32272660, 2020). "Images of PHAX expression in CK-positive tumour cells and CD31-positive ECs were taken in 10 random high-power fields (×40 magnification) and quantified in an unbiased manner, presented as corrected total fluorescence (CTF) intensity." (PMID 32272660, 2020). "In contrast, cultures treated with high dose sunitinib (100 and 200 μM) showed a statistically significant increase expression of PHAX in tumour cells (p < 0.001)." (PMID 32272660, 2020). "A significant increase in PHAX expression was evident in both ECs, tumour cells and in TECs in NK with sunitinib exposure in a dose-dependent manner." (PMID 32272660, 2020). "NK showed negligible PHAX expression; PHAX was mildly increased in ccRCC grade 1 tumours (* p < 0.05)." (PMID 32272660, 2020). "Immunofluorescence staining of patient tumours showed strong localisation of PHAX to the microvasculature consistent with the anti-angiogenic effect of sunitinib." (PMID 32272660, 2020). "Then, we demonstrated that PHAX protein expression in ECs, TECs, and tumour cells was increased by sunitinib in the organ cultures in a dose-dependent manner." (PMID 32272660, 2020). "PHAX expression was also seen in CK-negative infiltrating mononuclear cells within tumour and renal parenchyma interstitium in cultures treated with 100 μM sunitinib." (PMID 32272660, 2020). "Staining for PHAX was also seen in infiltrating mononuclear cells and in CD31-negative tumour cells." (PMID 32272660, 2020). "For example, we do not know whether the observed increased abundance of PHAX protein in higher grade tumours mediates an effect on sunitinib responsiveness." (PMID 32272660, 2020).
PHAX also shares sentences with these, for which no sentence is quoted: chronic thromboembolic pulmonary hypertension (1 paper); glioma (1); infection (1); malaria (1); Refsum disease (1); renal carcinoma (1).